LSM14A (LSM14A mRNA processing body assembly factor)
Description:
Essential for formation of P-bodies, cytoplasmic structures that provide storage sites for translationally inactive mRNAs and protect them from degradation. Acts as a repressor of mRNA translation. May play a role in mitotic spindle assembly.
Synonyms: C19orf13; FAM61A; RAP55; RAP55A; DKFZP434D1335
Tractability: PROTAC: ubiquitination databases record sites on it; its protein half-life has been measured.
Gene: Protein-coding gene on chromosome 19 (34,172,426 to 34,229,302, forward strand). Ensembl gene ENSG00000257103.
Subcellular location: Cytoplasm, P-body; Cytoplasm, cytoskeleton, spindle; Cytoplasm, Stress granule
Subcellular location (Human Protein Atlas): Cytoplasmic bodies; Cytosol
Gene Ontology:
Molecular function: protein binding; RNA binding; double-stranded DNA binding; double-stranded RNA binding; single-stranded RNA binding
Biological process: mitotic spindle assembly; negative regulation of translation; P-body assembly; stress granule assembly
Cellular component: cytoplasm; cytoplasmic ribonucleoprotein granule; cytoplasmic stress granule; cytosol; mitotic spindle; P-body; spindle
Genetic constraint (gnomAD): Loss-of-function variants: 12 observed, 43.34 expected, observed/expected ratio (o/e) 0.28, 90% interval 0.18 to 0.45. The upper end of that interval is the gene's LOEUF score, 0.45, which puts it in group 1 of 6, group 1 being the genes least tolerant of losing a copy. Missense variants: 367 observed, 531.89 expected, observed/expected ratio (o/e) 0.69, 90% interval 0.63 to 0.75. Synonymous variants: 165 observed, 183.81 expected, observed/expected ratio (o/e) 0.9, 90% interval 0.79 to 1.02.
Homologues: Orthologues: chimpanzee LSM14A (98% identical), dog LSM14A (98% identical), macaque LSM14A (98% identical), pig LSM14A (97% identical), guinea pig LSM14A (96% identical), mouse Lsm14a (93% identical), rat Lsm14a (93% identical), tropical clawed frog lsm14a (82% identical), zebrafish lsm14aa (69% identical), zebrafish lsm14ab (67% identical), Drosophila melanogaster tral (41% identical), Caenorhabditis elegans car-1 (35% identical). Paralogues in human: LSM14B (48% identical).
Diseases named in the same sentence as LSM14A in open-access papers:
LSM14A is named in the same sentence as 16 diseases in open-access papers, as found by Europe PMC text mining. Sharing a sentence is not in itself a finding about the gene and the disease. The quoted sentences say what the papers report.
viral infection (7 papers, 2020 to 2024). "LSM14A initiates cellular antiviral response in the early phase of viral infection by regulating MITA level in a cell-specific manner." (PMID 36563749, 2023). "Using SeV as an example of an RNA virus and herpes simplex virus-1 (HSV-1) as an example of a DNA virus, the 2012 study showed that LSM14A enhanced ISRE activity in response to virus infection." (PMID 32997711, 2020). "Additionally, LSm14A plays an important role in the early induction of IFN-beta during virus infection." (PMID 39330894, 2024). "Similarly, depletion of DDX6 or LSm14a, as might occur during the course of a viral infection, also results in P-body disassembly." (PMID 36877681, 2023). "Our studies indicated that LSM14A cleavage is mediated by 2Apro at a recognition site with a P1 ́ G. To validate this target site, we changed the P1 ́ glycine (G147) to either alanine (A) or glutamate (E) and tested if these mutants were cleaved upon virus infection." (PMID 32997711, 2020). "LSm14A, a member of the LSm family, is a sensor of viral RNA and DNA that regulates the IFN response through RIG-I, which plays an important role in initiating IFN-β induction during the early stages of viral infection." (PMID 39330894, 2024).
colon cancer (2 papers, 2021). "Therefore, we detected and confirmed that hypoxia increased the number of P-bodies in colon cancer cells by immunofluorescence assay using LSM14A as the marker of P-bodies." (PMID 33665193, 2021).
enterovirus infection (1 paper, 2020). "This diminished the utility of typical overexpression and knockout strategies to decipher the function of LSM14A during enterovirus infection." (PMID 32997711, 2020).
prostate carcinoma (1 paper, 2024). A carcinoma that arises from epithelial cells of the prostate gland. "Of note, EDC3 and LSM14A compete for binding to the P-body core protein DDX6, and P-body formation still occurs constitutively in EDC3 KO prostate cancer cells." (PMID 39046443, 2024).
PURA Syndrome (1 paper, 2023). "As PURA Syndrome is described to result from a haploinsufficiency and thereby lowered cellular PURA levels, our findings on PURA-dependent, LSM14A/DDX6-mediated P-body formation could potentially relate to a molecular dysfunction in patients." (PMID 36651277, 2023).
infection (4 papers, 2022 to 2024). The state of being infected such as from the introduction of a foreign agent such as serum, vaccine, antigenic substance or organism. "Similar to HNRNPM, RAI, LSM14A, LARP4, and CNOT2 showed complete loss of full-length protein during the course of infection." (PMID 38953667, 2024). "Moreover, the PB protein Lsm14A has been shown to bind to viral RNA/DNA after infection-induced PB disassembly to promote IRF3 activation and IFN-β production." (PMID 35998203, 2022). "By using IF/FISH (fluorescence in situ hybridization) methods, we showed co-localization of HA-tagged ZCCHC3, LSM14A, and the HIV-1 lentivirus gRNA in HeLa CD4+ cells 30 min after infection." (PMID 38384847, 2024). "Following infection with the all-in-one lentiviral sgRNA library and puromycin selection, oligomycin was added to induce P-bodies formation, and HEK293T cells with high LSM14A-GFP fluorescence intensity were selected for sgRNA sequencing." (PMID 38769438, 2024).
tumor (4 papers, 2017 to 2024). "By reexpression of PNRC1 or knockdown of P-body core genes (DDX6, DCP1A, and LSM14A), we determined that disruption of P-bodies attenuates cell proliferation, cell migration, and tumor growth induced by overexpression of YAP5SA in CRC." (PMID 39046443, 2024). "To further investigate the underlying role of LSM12, LSM14A, and LSM14B in tumor cell proliferation and invasion, we transfected SNU-387 cells with si-LSM12, si-LSM14A, and si-LSM14B RNAs." (PMID 35646684, 2022). "LSM12, LSM14A, and LSM14B overexpression is also associated with higher tumor-related immune checkpoints (e.g., PD-L1, B7-H3, and PVR) expression and increased therapeutic insensitivity to immune checkpoint blockade (ICB)." (PMID 35646684, 2022). "Fourteen of the mutated genes in this tumor are involved in metabolism (endogenous molecules as well as drugs), small molecule biochemistry, and cancer: AATF, ATF71P, CRIPAK, CROCC, CYP2A6, DOCK5, GPAT2, KRTAP4–9, LSM14A, MUC2, MYO1F, RHOQ, SUFU, and UTRN." (PMID 29259192, 2017). "Of note, we identified the potential inhibition effects of LSM12, LSM14A, and LSM14B on tumor immunity, which laid a novel foundation to further explore the role of LSM family members as novel potential therapeutic targets in HCC." (PMID 35646684, 2022). "Of note, higher expression of tumor-related immune checkpoints (e.g., PD-L1, B7-H3, and PVR) was also observed in tumors with LSM12, LSM14A, and LSM14B overexpression." (PMID 35646684, 2022). "We also found that tumors with higher expression of LSM12, LSM14A, and LSM14B had higher expression of tumor-related immune checkpoints (e.g., PD-L1, B7-H3, and PVR), which are important for the immunosuppressive phenotype in malignancies." (PMID 35646684, 2022). "The CCK-8 assay demonstrated that tumor cell proliferation was notably inhibited in LSM12, LSM14A, and LSM14B depleted SNU-387 cells (P <0.0001)." (PMID 35646684, 2022). "Taken together, these findings suggest the critical pro-tumor effects of LSM12, LSM14A, and LSM14B overexpression on HCC tumor cell proliferation and metastasis." (PMID 35646684, 2022). "Additionally, we preliminarily demonstrated knockdown of LSM12, LSM14A, and LSM14B significantly inhibited tumor cell proliferation and invasion." (PMID 35646684, 2022). "Interestingly, LSM12, LSM14A, and LSM14B were observed to play critical roles in the T-cell receptor signaling pathway, suggesting their potential effects on tumor immunity in HCC." (PMID 35646684, 2022).
cancer (2 papers, 2017 to 2024). A tumor composed of atypical neoplastic, often pleomorphic cells that invade other tissues. "Strikingly, knockout of the P-body-nucleation-determining genes DDX6 and LSM14A inhibited proliferation in multiple cancer cell lines (negative Chronos score)." (PMID 39046443, 2024).
LSM14A also shares sentences with these, for which no sentence is quoted: adenoid cystic carcinoma (1 paper); breast carcinoma (1); esophageal carcinoma (1); lung adenocarcinoma (1); Lynch syndrome (1); mental retardation (1); stomach adenocarcinoma (1); uterine corpus endometrial carcinoma (1).